ZIC1 (Zic family zinc finger 1)
Diseases named in the same sentence as ZIC1 in open-access papers (continued):
Sharing a sentence is not in itself a finding about the gene and the disease.
medulloblastoma (continued). "Concordantly, expression of ZIC1 represses malignant phenotypes in G3/G4 medulloblastoma while enhancing malignant phenotypes in SHH medulloblastoma in model systems." (PMID 39753768, 2025). "SHH medulloblastoma ZIC1 mutants show increased activity versus wild-type ZIC1, whereas G4 medulloblastoma ZIC1 mutants exhibit LOF phenotypes." (PMID 39753768, 2025). "WT ZIC1 overexpression led to activation of pathways involved in development and organogenesis, which was dampened with the G4 medulloblastoma ZIC1 mutants but further augmented with the SHH medulloblastoma ZIC1 mutants." (PMID 39753768, 2025). "Recently, ZIC1 has also been found to participate in the progression of human cancers, including medulloblastomas, endometrial cancers, and mesenchymal neoplasms." (PMID 21347233, 2011). "Despite its role in neural development, ZIC1 was also found to participate in the progression of human cancers, such as medulloblastoma, endometrial cancers, and mesenchymal neoplasms." (PMID 21347233, 2011). "ZIC1 is predominantly expressed in medulloblastoma, and ZIC2 expression is down-regulated in medulloblastoma compared to its mRNA level in normal cerebellum." (PMID 20199689, 2010). "The abundance of the ZIC1 protein in medulloblastoma is considered to reflect the properties of the cell of origin, cerebellar granule neuron." (PMID 20199689, 2010). "We hypothesized therefore that somatic repression of ZIC1 through acquisition of the ‘H3K27ac–H3K27me3 hemizygous state’ is a chromatin-based driver event in G4 medulloblastoma." (PMID 39753768, 2025). "The genetic and chromatin variants of ZIC1 and ZIC4 in G4 and SHH medulloblastoma suggest a model in which the activity of ZIC TFs has context-dependent roles in UBC and granule neuron lineage cells, which cumulatively constitute the majority of the neurons in a human brain." (PMID 39753768, 2025). "We now demonstrate that ZIC1 mutations in medulloblastoma are context dependent, with loss-of-function (LOF) mutations and epigenetic alterations in G4 medulloblastoma, contrasted with GOF mutations in SHH medulloblastoma." (PMID 39753768, 2025). "Examination of ZIC1 VAF from our published medulloblastoma RNA-seq cohort produced similar results." (PMID 39753768, 2025). "Contrary to ZIC1 suppressing the growth of G3 medulloblastoma, we hypothesized that ZIC1 would promote the growth of SHH medulloblastoma." (PMID 39753768, 2025). "G3/G4 medulloblastoma tumors exhibit a spectrum of ZIC1 expression levels as well as differentiation signatures, with G4 medulloblastoma exhibiting higher levels of both, potentially rehighlighting the known role of ZIC1 in cerebellar development." (PMID 39753768, 2025). "Our observation that the ZIC1/ZIC4 locus undergoes recurrent repression in G4 medulloblastoma through hemizygous deposition of H3K27me3 on its SE prompted us to look for additional mono-allelic SEs in a cohort of 51 medulloblastoma tumors with matching H3K27ac ChIP–seq and WGS data." (PMID 39753768, 2025). "Overexpression of ZIC1 suppresses the growth of group 3 medulloblastoma models, whereas it promotes the proliferation of SHH medulloblastoma precursor cells." (PMID 39753768, 2025). "Interestingly, the fraction of M2 macrophages in Group 4 medulloblastoma were positively correlated with the risk score and were significantly correlated with the expression level of four signature genes (CCNY, SYNE3, CYB5D2, and SELENOV) and four hub genes (GLI2, PAX6, RUNX2, and ZIC1)." (PMID 32508873, 2020). "ZIC1, −2 and −5 are over-expressed in meningiomas, while ZIC4 is over-expressed in medulloblastomas." (PMID 27191985, 2016). "RT-PCR analysis revealed that ZIC4 expression is highly enhanced in medulloblastoma, in a sharp contrast to the expression levels in whole brain, while ZIC1, ZIC2 and ZIC5 are expressed both in the meningioma and medulloblastoma." (PMID 20199689, 2010).
medulloblastoma (continued). "ZIC1, ZIC2, and ZIC5 are novel molecular markers for meningiomas whereas ZIC4 expression is highly selective for medulloblastomas." (PMID 20199689, 2010). "Notably, 37 of the superenhancers had known Group 3 and 4 medulloblastoma drivers as their nearest genes, including CHD7, CBFA2T2, GSE1, and of course, OTX2, and ZIC1." (PMID 41279093, 2025). "This pattern was associated with reduced ZIC1/ZIC4 transcript levels and was not recurrently observed in either SHH or WNT medulloblastoma." (PMID 39753768, 2025). "ZIC1, ZIC2 and ZIC5 transcript levels in meningiomas were higher than those in whole brain or normal dura mater, whereas all five ZIC genes were abundantly expressed in medulloblastomas." (PMID 20199689, 2010). "Because the ZIC1/ZIC4 locus can be targeted by both genetic- and chromatin-based mechanisms, we examined the overall proportion of samples within the validation cohort medulloblastomas (251 tumors with RNA-seq and WGS) affected by either chromatin or genetic variants." (PMID 39753768, 2025). "Due to the lack of accurate, robust G4 medulloblastoma cell lines, we examined the functional importance of ZIC1/ZIC4 by overexpressing blue fluorescence protein (BFP) empty vector, ZIC1, ZIC4 or ZIC1 and ZIC4 together in D425 and D283 G3 medulloblastoma cell lines." (PMID 39753768, 2025). "Overexpression of ZIC1/ZIC4 in G3 medulloblastoma lines followed by transcriptional profiling revealed increased expression of genes involved in neuronal differentiation, consistent with a model in which LOF of ZIC1/ZIC4 might hinder differentiation." (PMID 39753768, 2025). "We conclude that haploinsufficiency of ZIC1 due to either germline or somatic events, with consequent diminished transcription, has critical effects on the biology of the rhombic lip, either in toto (DWM) or possibly in distinct somatic subclones (medulloblastoma)." (PMID 39753768, 2025). "Notably, we observe cases of G4 medulloblastoma with mono-allelic ZIC1/ZIC4 expression but without H3K27me3 deposition, suggesting that additional cryptogenic genetic/epigenetic routes to allelic silencing of ZIC1/ZIC4 exist." (PMID 39753768, 2025).
ovarian carcinoma (7 papers, 2009 to 2025). A malignant neoplasm originating from the surface ovarian epithelium. "In ovarian cancer (OC), silencing of ZIC1 and ZIC4 hypermethylation was associated with a poor prognosis, and their repression was correlated with increased proliferation, migration, and invasion in a panel of OC cell lines." (PMID 40952541, 2025). "ZIC1 promoter methylation has also been suggested as a potential prognostic marker in ovarian cancer." (PMID 25472429, 2014). "ZIC encoding genes have been previously implicated in cancer development and ZIC1 is known to transcriptionally trans-activate apolipoprotein E (APOE) - a gene previously implicated in the proliferation and survival of ovarian cancer cells." (PMID 20040092, 2009). "MethylCap-Seq has been applied to analyze methylomic patterns of ovarian tumors and results suggest that hedgehog signaling pathway members (ZIC1 and ZIC4) are DNA methylation prognostic biomarkers for ovarian cancer." (PMID 24782983, 2014).
cervical cancer (5 papers, 2019 to 2024). A primary or metastatic malignant neoplasm involving the cervix. "Recent studies found that the levels of ZIC1 mRNA and protein in cervical cancer and increased CIN grade were significantly decreased compared with normal and CIN samples, which is presumably a promising biomarker for prognosis." (PMID 38031140, 2023). "We tested for DNA hypermethylation in promoter regions of GHSR, SST, and ZIC1, which enables the accurate detection of both bladder and cervical cancer in urine." (PMID 33572525, 2021). "At the threshold corresponding to 80% specificity in controls, all 6 DNA methylation markers revealed a high sensitivity varying from 76% (FAM19A4 and PHACTR3) to 83% (PRDM14 and ZIC1) for cervical cancer detection in urine sediments." (PMID 30816167, 2019). "Single methylation of LOC100289333 (LOC100289333m), ZIC1 (ZIC1m) and SOX1 (SOX1m) tested positive in all cervical cancer scrapings." (PMID 38031140, 2023). "Urine samples (27 controls, 30 CIN3 and 17 cervical cancer) were processed into 3 fractions and tested for 5 methylation markers (ASCL1, GHSR, LHX8, SST, ZIC1)." (PMID 32171935, 2020).
colorectal cancer (5 papers, 2011 to 2021). A primary or metastatic malignant neoplasm that affects the colon or rectum. "In addition, ZIC1 potentially serves as a tumour suppressor by inhibiting cell proliferation in gastric and colorectal cancer cells." (PMID 22799764, 2012). "It is becoming clear that as a zinc finger transcription factor, ZIC1 may modulate multiple downstream genes in neural tissue, colorectal cancer and liposarcoma cells." (PMID 22799764, 2012). "Clinicopathological features of ZIC1 methylation in colorectal cancer." (PMID 21347233, 2011). "Taken together, our results suggest that ZIC1 may potentially function as a tumor suppressor gene, which is downregulated through promoter hypermethylation in colorectal cancers." (PMID 21347233, 2011). "ZIC1 was also downregulated and frequently hypermethylated in primary colorectal cancer tissues." (PMID 21347233, 2011). "ZIC1 expression is also significantly downregulated in primary colorectal cancer tissues relative to adjacent non-tumor tissues (p = 0.0001)." (PMID 21347233, 2011).
bladder cancer (4 papers, 2017 to 2022). "All nine urinary methylation markers (FAM19A4, GHSR, MAL, miR-129, miR-935, PHACTR3, PRDM14, SST and ZIC1) showed significantly higher methylation levels in bladder cancer patients than in controls (p < 0.001)." (PMID 35123558, 2022). "The urinary methylation levels of FAM19A4, GHSR, MAL, miR-129, miR-935, PHACTR3, PRDM14, SST and ZIC1 were significantly higher in patients with bladder cancer than in controls (all, p < 0.001)." (PMID 35123558, 2022). "We found that the methylation levels of markers GHSR, SST, and ZIC1 were higher in natural voided urine (all, Mann–Whitney U test: p < 0.001) of bladder cancer patients than in the natural voided urine of benign hematuria controls." (PMID 33572525, 2021). "These encompass seven protein-coding genes (FAM19A4, GHSR, MAL, PHACTR3, PRDM14, SST and ZIC1)—of which, the CpG islands are methylated in bladder cancer—as well as two miRNAs (miR-129 and miR-935) with promoter regions that are also known to be methylated in bladder cancer." (PMID 32252299, 2020).
glioblastoma (4 papers, 2010 to 2022). The most malignant astrocytic tumor (WHO grade IV). "While either SOX11 or ZIC1 promotes the expression of TUBB3/βIII-tubulin and induces a neuronal phenotype in U87 glioblastoma cells, the expression of ZIC1 greatly enhances the impact SOX11 has on TUBB3 expression and neuronal differentiation." (PMID 35573698, 2022). "High expression levels of ZIC1/5 were associated with poor OS in brain low-grade glioma (LGG) patients, while low ZIC3 expression combined was related to favorable OS in glioblastoma multiforme (GBM)." (PMID 34475426, 2021). "The mRNA expression of ZIC1 were highly expressed in glioblastoma patients, and ZIC3 and ZIC4 were downregulated expression." (PMID 34475426, 2021).
meningioma (4 papers, 2010 to 2023). A generally slow growing tumor attached to the dura mater. "The expression level of ZIC1 in public microarray data was greater in meningiomas classified as World Health Organization Grade II (atypical) than those classified as Grade I (benign)." (PMID 20199689, 2010). "Immunoscreening using anti-ZIC antibodies revealed that 23 out of 23 meningioma cases were ZIC1/2/3/5-immunopositive." (PMID 20199689, 2010). "Our results indicate that the expression of ZIC1, ZIC2 and ZIC5 is a conserved feature of meningioma." (PMID 20199689, 2010). "This is consistent with our observation that ZIC1, ZIC2 and ZIC5 mRNA levels are higher in meningiomas than in normal brain tissues." (PMID 20199689, 2010). "We examined the mRNA and protein expression of human ZIC1, ZIC2, ZIC3, ZIC4 and ZIC5 genes in meningiomas in comparison to other brain tumors, using RT-PCR, analysis of published microarray data, and immunostaining." (PMID 20199689, 2010). "The transcriptional levels of ZIC1, ZIC2, and ZIC5 in meningiomas were found to be significantly higher than those in normal dura mater and could serve as new molecular markers for meningiomas." (PMID 37479694, 2023). "The mRNA levels of ZIC1, ZIC2 and ZIC5 were higher in meningioma than in dura mater." (PMID 20199689, 2010).
colon cancer (3 papers, 2011 to 2021). "ZIC1 has been shown to counteract with Gli (glioma-associated oncogene homolog 1), which functions as downstream of sonic hedgehog (Shh) signaling pathway and participate in the progression of colon cancer." (PMID 21347233, 2011). "Our results suggest that induction of apoptosis by ZIC1 may be associated with Bcl-xl/Bad/Caspase3 cascade in colon cancer cells." (PMID 21347233, 2011). "To search for target genes of ZIC1 in colon cancer cells, we utilized cDNA microarray to analyze gene expression profile changes induced by ectopic expression of ZIC1." (PMID 21347233, 2011). "In summary, we revealed that a novel tumor suppressor gene ZIC1 was inactivated through promoter methylation in colon cancer cells." (PMID 21347233, 2011). "In this study, we demonstrate ZIC1 to be silenced or significantly downregulated in colon cancer cell lines." (PMID 21347233, 2011). "To confirm the expression pattern observed in the microarray, we validated the expression of 10 selected genes in colon cancer cells transfected with ZIC1 by qRT-PCR." (PMID 21347233, 2011). "Here, our results show that exogenous ZIC1 inhibits cell proliferation through p-Akt and p-Erk1/2 inactivation in colon cancer cells." (PMID 21347233, 2011). "To explore the effect of ZIC1 on cell proliferation in colon cancer, we performed cell viability and colony formation assays in CRC cell lines." (PMID 21347233, 2011). "Here, we report that ZIC1 promoter is frequently methylated in CRCs tissues and colon cancer cell lines." (PMID 21347233, 2011). "In the present study, we found that ZIC1 was silenced or downregulated in colon cancer cell lines, as well as in primary tumor tissues relative to adjacent non-tumor tissues (p<0.05)." (PMID 21347233, 2011). "Semi-quantitative RT-PCR showed that ZIC1 transcript was silenced or downregulated in all of colon cancer cell lines when compared to normal colon tissue." (PMID 21347233, 2011). "To determine whether ZIC1 is silenced by promoter hypermethylation in colon cancer, we examined the expression of ZIC1 mRNA in six colon cancer cell lines." (PMID 21347233, 2011). "In addition, we found that ectopic expression of ZIC1 can induce apoptosis of colon cancer cells." (PMID 21347233, 2011). "In an attempt to identify downstream targets of ZIC1 in CRCs, we analyzed the gene expression profiles of colon cancer cells with or without ZIC1 overexpression." (PMID 21347233, 2011). "The demethylation treatment by Aza dramatically restored the expression of ZIC1 mRNA in a subset of colon cancer cells (HCT116, HT29 and SW620), implicating that DNA methylation may be involved in the regulation of ZIC1 expression." (PMID 21347233, 2011). "However, the function of ZIC1 in colon cancer progression has not been defined." (PMID 21347233, 2011). "Thus, ZIC1 may mediate cell proliferation through PI3K/Akt and MAPK pathways in colon cancer cells." (PMID 21347233, 2011).
glioma (3 papers, 2021 to 2024). A benign or malignant brain and spinal cord tumor that arises from glial cells (astrocytes, oligodendrocytes, ependymal cells). "PAX3, which has been implicated in glioma tumorigenesis is co-expressed with ZIC1." (PMID 34475426, 2021). "Significant upregulation of ZIC1/3/4 was found in brain low-grade glioma patients, while ZIC5 was downregulated." (PMID 34475426, 2021). "After exploring the immune cell infiltration of ZICs in glioma patients, functional enrichment analysis were construct using the genes that were coexpressed with ZIC1/5 and ZIC3 in LGG and GBM, individually." (PMID 34475426, 2021). "Biological processes such as embryonic skeletal system development (GO: 0048706), response to radiation (GO: 0009314), and sensory organ morphogenesis (GO: 0090596) were significantly regulated by ZIC1 alterations in glioma." (PMID 34475426, 2021). "The expression levels of ZIC1/3/4/5 in gliomas were significantly different from those in normal samples." (PMID 34475426, 2021). "The neural development-associated TFs, ZIC1, ZIC2, and ZIC3, were specifically expressed in glioma." (PMID 39345334, 2024). "Our results identified ZIC1/3/5 as novel biomarkers and potential therapeutic targets for glioma." (PMID 34475426, 2021). "According to information provided by the HPA database, ZIC1 was highly expressed in normal brain tissues, and higher expression of ZIC was observed in malignant low-grade glioma than in normal tissues." (PMID 34475426, 2021). "Taken together, our results showed that the gene expression of ZIC1 and ZIC3 were obviously different between glioma and normal samples, and the evidence of gene protein expression was not sufficient which needed further experimental verification.." (PMID 34475426, 2021).
Intellectual disability (3 papers, 2013 to 2026). "ZIC1, which was significantly up-regulated in FGF8-treated organoids, is implicated in complex syndromes involving cortical, callosal, and cerebellar malformations associated with intellectual disability." (PMID 39485283, 2024). "We also detected a 3q deletion including ZIC1 and ZIC4 in a patient who underwent SNP-array analysis for intellectual disability and dysmorphisms." (PMID 23679990, 2013).
thyroid cancer (3 papers, 2016 to 2024). "ZIC1 is also a tumor suppressor gene in thyroid cancer by blocking the activities of the PI3K/Akt and MAPK signaling pathways and the transcription of transcription factor FOXO3a." (PMID 29723302, 2018). "We have previously demonstrated that ZIC1 not only inhibits phosphorylation of Akt and Erk, but also increases FOXO3a transcriptional activity in thyroid cancer cells." (PMID 27458157, 2016). "Interestingly, Zic1 has been described as a tumor suppressor in various cancers such as CRC, GC and thyroid cancer (TC), through its downregulation mainly by epigenetic regulation." (PMID 39125691, 2024).
brain malformations (2 papers, 2016 to 2019). "Suspecting a possible involvement of the maternal ZIC1 gene variant, we suggested an immediate brain MRI examination of the mother, where it was revealed that she presents with the same structural brain malformations detected in all three fetuses." (PMID 27168972, 2016).
breast carcinoma (2 papers, 2011 to 2022). "Analysis of transcriptional profiles of large cohorts of human tumors revealed that ZIC1 mRNA is overexpressed in poorly differentiated carcinomas, including breast cancers." (PMID 21952072, 2011).
CHARGE syndrome (2 papers, 2017 to 2024). CHARGE syndrome is a multiple congenital anomaly syndrome characterized by the variable combination of multiple anomalies, mainly Coloboma; Choanal atresia/stenosis; Cranial nerve dysfunction; Characteristic ear anomalies (known as the major 4 C's). "The altered cerebellar foliation pattern in Chd7 haploinsufficient mice show some similarities to those reported in mice with altered Engrailed, Fgf8 or Zic1 gene expression and we propose that mutations or polymorphisms in these genes may modify the cerebellar phenotype in CHARGE syndrome." (PMID 29168327, 2017). "Zic1/4 are responsible for cerebellar vermis anomalies in Dandy–Walker syndrome, which is also a phenotype of CHARGE syndrome." (PMID 39418292, 2024).